CTLA4 (cytotoxic T-lymphocyte associated protein 4)
Diseases named in the same sentence as CTLA4 in open-access papers (continued):
Sharing a sentence is not in itself a finding about the gene and the disease.
tumor (continued). "On tumor infiltrating immune cells, A2AR was found to correlate positively with PD-1 and negatively with CTLA-4." (PMID 37753093, 2023). "ZVI-NP enhanced anti-tumor immunity via reduction of Treg cells and promotion of M2 macrophages to M1, and repression of PD1 and CTLA4 in CD8+ T cells, as well as reduction of PD-L1 expression in tumor cells." (PMID 37033636, 2023). "Treatment of anti-CTLA4 in combination with cisplatin and anti-PD-1 enhanced antitumor immunity in TNBC, involved with activation of tumor-infiltrating cytotoxic CD8 and CD4 T cells." (PMID 37838657, 2023). "Checkpoint inhibitors, such as Pembrolizumab (anti-programmed cell death protein-1; PD-1) and Ipilimumab (anti-cytotoxic T-lymphocyte associated protein 4; CTLA4) bind to immune cells rather than directly to the tumour, and therefore may not require interactions with activating FcγRs." (PMID 37652365, 2023). "In our discovery cohort, we evaluated the expression profiles of CMTM6, PD-L1, CTLA-4, and FOXP3 in 177 HNSCCs from Caucasian patients of all tumor stages and different treatment regimens, correlating marker expression in tumor and immune cells with outcomes." (PMID 38067301, 2023). "LAG3 was the most promising immune checkpoint after PD-1 and CTLA-4, and higher LAG3 and FGL1 expression promoted tumor growth by suppressing the immune microenvironment." (PMID 36843949, 2023). "Looking at B‐lymphocytes, dendritic cells, tumor‐infiltrating macrophages, neutrophils, and other immune checkpoints, such as PDL1, CTLA4, ICOS, and VISTA, would have been more informative." (PMID 37092584, 2023). "The cells in seqC1_FoxP3int had a relatively low expression of FoxP3, CD25, CTLA-4, HLA-DR, PD-1 and IL-10, and a high expression of IL-17, indicating that these may be pro-inflammatory Tregs induced in an inflammatory microenvironment in these tumor and lymph node tissues." (PMID 37232845, 2023). "PD-L1 expression in tumor cells correlated with CD8 + T cells and macrophages in the TME and IFN-γ expression with suppressive CTLA4+/IFNγ+ immune cells in the TME and LN." (PMID 36979688, 2023). "Immune checkpoint blockade (ICB) therapy employs ICIs to target and block CTLA-4 and/or PD-1 receptors on immune cells or their ligands—CD80/CD86 and PD-L1—on tumor cells to enhance T cell activation and antigen-specific response." (PMID 37587450, 2023). "Many immune-related therapeutic indicators, including PD-1, PD-L1, HER2, IGF2R, CTLA-4, and GD2, are highly expressed in tumor samples." (PMID 36830696, 2023). "The findings of our paper confirm a notable synergistic effect of anti-CTLA-4 Nb-modified liposomes-based CTLA-4 checkpoint blockade and CD8+ T cells activated by the DC/tumor fusion vaccine." (PMID 37419930, 2023). "In this study, the expression of KIFC1 was positive with immune checkpoints like CTLA4, CD276, and LAG3 in most tumor types." (PMID 38112634, 2023). "Currently, four types of ICIs (anti-PD-1, PD-L1, CTLA-4, and LAG-3 mAbs) have been approved by the FDA for tumor treatment." (PMID 37670328, 2023). "Combination therapy did not affect the proportion of PD-1+ CD8+ T cells but reduced the frequency of CTLA-4+ and Tim-3+ CD8+ T cells as compared to the tumor-bearing group." (PMID 37108179, 2023). "PD-L1(PDCD1), CTLA4 and PD1 (CD274) are important immune checkpoints which are in charge of tumor immune escape.Taken the potential carcinogenic function of HHIP in CRC into consideration, the correlation of HHIP with PD-L1, CTLA4 and PD1 was assessed." (PMID 37568084, 2023). "Anti-CTLA4 antibodies not only block the interaction between CTLA4 and CD80/86 but also consume Tregs, thereby promoting the costimulation and amplification of tumor-specific CTLs and improving clinical benefits." (PMID 37649123, 2023).
tumor (continued). "Accordingly, improved antitumor efficacy has been observed with the combination of anti-PD-1 or anti-CTLA-4 in the context of ICOS co-stimulation (i.e., forced ICOSL expression and/or ICOS agonist antibody) in mouse syngeneic tumor models." (PMID 36266600, 2023). "Mice showed tumor remission with CRT-NP (~30% vs. control) and anti-CTLA-4 (~20% vs. control) treatment." (PMID 37376141, 2023). "For example, Belinostat has recently been shown to improve the efficacy of anti-CTLA-4 monotherapy and anti-CTLA-4 combined with anti-PD-1/PD-L1 in HCC patients, leading to complete tumor rejection." (PMID 37304265, 2023). "FOXP3+CD4+ Tregs mostly exist in the blood, whereas CTLA4+CD4+ Tregs clone and amplify locally within tumors, indicating local clonal expansion of tumor-resident Tregs." (PMID 37187731, 2023). "A single fraction of 20 Gy was delivered using whole-tumor radiation or GRID alone or in combination with antibodies against immune checkpoints PD1 and CTLA-4." (PMID 37979032, 2023). "CTLA-4 is also an inhibitory receptor on the surface of FOXP3+ Treg cells, which are important components of the tumor microenvironment (TME)." (PMID 36765522, 2023). "Immunotherapy is also thought to have potential applications in OS and many immune-related therapeutic indicators, including PD-1, PD-L1, HER2, IGF2R, CTLA-4, and GD2, are highly expressed in tumor samples." (PMID 36830696, 2023). "In patients taking anti-PD-1 and anti-CTLA-4 therapy, the poorer the ICI response, the higher the tumor TIDE score." (PMID 37033251, 2023). "In contrast to effector T cells, NK cells, DCs, and M1 macrophages, Tregs comprise tumor-promoting immune cells in which the suppressive activity is mediated by key molecules including IL-10, TGF-β, CTLA4, and IL-35." (PMID 38136421, 2023). "The efficacy of anti‐CTLA‐4 TGF‐βRIIecd in reducing Treg activity in TME and hampering tumour progression is superior to that for the CTLA‐4 inhibitor ipilimumab." (PMID 36625080, 2023). "Few studies published their results on CTL4-A (CD152) labelling with 64Cu, and demonstrated good visualization of cytotoxic T-lymphocyte antigen-4 (CTLA-4) on the T cell infiltrating tumor." (PMID 37174086, 2023). "The major immune checkpoints include PDCD-1, CD274 (also known as PD-L1), CTLA-4, HAVCR2 (also called TIM-3), LAG-3 and TIGIT which are responsible for tumor immune escape." (PMID 37810780, 2023). "Theragnostic biomarkers like IDO1, s-CTLA-4, IFN-γ, TNF-α and IL-2 have been studied in various tumors, and seems to hold significant potential in mapping the tumor microenvironment and predicting response to ICPIs." (PMID 36879122, 2023). "Based on IHC expression of immune co-inhibitory molecules in our cohort, tumor cells of SCLC were found to be poor immuno-expresser of PD-L1 and IDO1, while CTLA-4 immunolabelling was seen in a fair number of cases." (PMID 36879122, 2023). "The infiltration of CD4 and CD8 T cells, as well as the levels of the TEX marker genes (HAVCR2, TIGIT, CTLA4, LAG3, and PD1) and tumor stem cell marker genes (CD44 and PROM1), were all greater in tissue samples with high TEXSRGs-score." (PMID 37957420, 2023). "In 1996, James Allison and his team discovered that administering antibodies blocking CTLA-4 interaction with CD28 led to increased T-cell activation and tumor rejection." (PMID 37420216, 2023). "An increasing number of studies have showed that various immune checkpoint receptors, such as PD-1, CTLA4, TIGIT, TIM3, LAG3, and inflammatory factors, are expressed and altered in the tumor microenvironment." (PMID 38110467, 2023). "The regulation of immune checkpoints such as PD-1, CTLA-4, TIM-3 and TIGIT is highly dependent on tumor type." (PMID 36798129, 2023). "Consistently, the features for suppression of anti-tumor immunity were dominantly elevated in the CDC20-high group, such as BTLA, CTLA4, CD4, ITGAM, C4B, CD163, and CD206." (PMID 37528490, 2023).
tumor (continued). "The anti-CTLA-4, on the other hand, stimulates IFN-γ production, which in turn kills tumor cells more effectively." (PMID 36766849, 2023). "Possible therapeutic strategies include checkpoint blockade, e.g., blockade of CTLA-4, PD1, PD-L1; targeting angiogenesis, e.g., anti-VEGF drugs; or inhibiting tumor-specific metabolic pathways, e.g., IDO1 inhibitors." (PMID 37427115, 2023). "A comprehensive analysis of a database and immunohistochemistry of tumor tissues from a cohort of 290 ICCA patients revealed that CTLA-4+ TILs and PDL1+ TILs independently predict tumor recurrence and OS in iCCA patients after surgical tumor removal." (PMID 38213535, 2023). "The therapeutic use of antibodies that neutralize CTLA-4, PD-1, or PDL-1 binding sustain T-cell activation in the tumor microenvironment and improve cytotoxic response and protection against tumor growth." (PMID 37038035, 2023). "Interaction between CTLA-4 on T cells and CD80 on tumor cells leads to protein kinase B (Akt) pathway inhibition and IL-2 function in T cells." (PMID 36816749, 2023). "Combining these therapies is not only biologically compelling for their anti-tumor efficacy but also to reduce the toxicity of each monotherapy, making the anti-CD137/anti-CTLA-4 combination the top choice for clinical translation." (PMID 37334375, 2023). "More importantly, a recent study assessing the therapeutic implication of ipilimumab, a CTLA-4 antibody, showed that ipilimumab increased the frequency of LAG-3 expression on tumor-infiltrating cells in metastatic melanoma patients." (PMID 37509517, 2023). "The authors observed a significant reduction in serum anti-CTLA-4 levels and effective tumor growth inhibition in CT26 tumor-bearing mice receiving the hydrogel peritumorally." (PMID 37504472, 2023). "Our results showed that tumor targeting-related immune checkpoint genes such as CD274 (p = 0.0137), TGFB1 (p = 0.0175), PDCD1 (p < 0.001), CTLA4 (p < 0.001), and LAG3 (p < 0.001) were significantly associated with APOC1." (PMID 36969562, 2023). "He and co-workers also encapsulated DOX, dual ICB antibodies, anti-CTLA-4 and anti-PD-1, into the mPEG-b-PELG hydrogel as a system for tumor immunotherapy and prevention of post-surgical tumor reoccurrence." (PMID 37265604, 2023). "Tregs overexpress FoxP3, a transcription factor associated with the up-regulation of CTLA-4 on the cell surface; CTLA-4 binds to CD80 expressed by antigen-presenting cells and inhibits cytotoxic T-cell activation, contributing to tumor development." (PMID 37324191, 2023). "Further comparison of immune infiltration, tumor mutation load, and immunophenoscore (IPS) comparison between the 2 groups indicates that the high-risk group could potentially demonstrate a heightened sensitivity towards immunotherapy checkpoints PD-1, CTLA-4, IL-6, and LAG3 in ccRCC patients." (PMID 37653791, 2023). "Compared to Trm within adjacent normal tissues, Trm within tumors was found to increase the expression of dysfunctional markers such as TIM-3, PD-1, CTLA-4 and LAYN, suggesting that they have experienced with tumor antigens." (PMID 37881432, 2023). "Ipilimumab is a human monoclonal IgG1 antibody against CTLA-4, which blocks the immunosuppressive interaction between CTLA-4 and its ligands on cells (CD80/CD86) to promote the activation and proliferation of T cells, and enhance anti-tumor immune function." (PMID 37063927, 2023). "Immune checkpoint inhibitors have garnered substantial attention as a therapeutic strategy, with notable immune checkpoints, including CTLA4, PD-1, PD-L1, and LAG3, identified as effective targets for stimulating T cell-mediated anti-tumor immunity." (PMID 38162499, 2023). "Tumor biopsies collected at baseline were denoted as B-ICC, while those treated with ICBs (PD-1 or PD-L1/CTLA-4) were marked as T-ICC." (PMID 36899373, 2023).
tumor (continued). "The successful priming of T-cells leads to enhanced primary tumor control and promotes abscopal responses at metastatic tumor sites, especially when combined with checkpoint inhibitors, such as anti-PD1 and anti-CTLA-4." (PMID 37289257, 2023). "Preclinical experiments in humanized animal tumor models demonstrated antitumor activities of QL1706, with evidence of a functional dual blockade of both the PD-1 and CTLA-4 pathways." (PMID 37158938, 2023). "Immune checkpoint proteins such as CTLA4 and PD1 play an important role in suppressing T‐cell activation and limiting the immune response which make tumor cells “escape” the immune surveillance." (PMID 37814950, 2023). "All immune checkpoints were significantly different between the normal and tumor groups (P < 0.05), in which PDCD1, CTLA4, and HAVCR2 were highly expressed in tumor tissues, while CD274, LAG3, and PDCD1LG2 were highly expressed in normal tissues." (PMID 37872211, 2023). "The remarkably increase in the survival of mice with CT26 tumours treated with the combination of αCTLA-4 with redaporfin-PDT can be assigned to the high surface expression of CD80 and unchanged expression of CTLA-4 post-PDT." (PMID 37468749, 2023). "When CTLA-4 engages with its ligands, CD80 and CD86, similarly to CD28, the coinhibitory response will be activated and the tumor cell will escape the host immune surveillance system." (PMID 37025485, 2023). "CD28 and CTLA4 expressed on T lymphocytes share identical ligands, CD80 and CD86, on tumor cells or antigen-presenting cells." (PMID 36983005, 2023). "ICI therapy aims to overcome tumor immune escape through targeting immune inhibitory molecules (e.g., PD-1, PD-L1, LAG3, and CTLA4) expressed on the surfaces of tumor and immune cells." (PMID 37190216, 2023). "Clone 87CAB3 demonstrated equivalent anti-tumor efficacy as the parental CTLA-4 (ipilimumab analogue, “IpA”) in syngeneic MC38 tumors implanted into human CTLA-4 knock-in mice." (PMID 37753969, 2023). "Immune checkpoint molecules, such as PD-L1, CTLA-4 and CD47, are important regulators that induce tumour cell immune escape." (PMID 36902476, 2023). "The immunological checkpoints selected for the analysis, such as PD-1/PD-L1, CTLA-4/CD86, and CD200R/CD200, play a significant role in regulating the immune response in many diseases, including cancer, and influencing the tumor microenvironment." (PMID 37835480, 2023). "This suggests that when anti-PD-1, anti-CTLA-4 or anti-PD-1/anti-CTLA-4 in combination is used alone, tumor cells can develop immune resistance through compensatory upregulation of the immunosuppressive molecule LAG-3 and reduce the therapeutic effect." (PMID 38026944, 2023). "CTLA-4 and PD1/PD-L1 are important immune checkpoints that are related to the effect of tumor immunotherapy." (PMID 37848987, 2023). "Another preclinical study showed that the IDO inhibitor 1-MT enhanced the efficacy of anti-CTLA-4 and anti-PD-1/PD-L1 treatments by increasing the infiltration and activation of CD8 + T cells at the tumor site." (PMID 37924140, 2023). "The immune checkpoints PD1, PD-L1, CTLA-4, and TIGIT play instrumental roles in tumor immune escape." (PMID 36637946, 2023). "Checkpoint receptors on T and natural killer (NK) cells, including CTLA-4 and LAG-3, were highly expressed even in tumor-adjacent and normal tissues of liver, coincident with higher levels of B7-H3 and ARG1." (PMID 37768208, 2023). "Considering the close relationship of SEMA3G with tumor immune infiltration in KIRC, we further assessed the correlation of SEMA3G expression with the levels of immune checkpoints (PD-1, PD-L1 and CTLA4)." (PMID 38070142, 2023). "For example, the binding of PD-L1 to immune checkpoint PD-1, as well as the binding of CTLA-4 to CD80/CD86 ligands, are key inhibitory checkpoint signals that limit T cell activation and block its action on tumor cells." (PMID 37789267, 2023).
tumor (continued). "In an in vivo study, ipilimumab and tremelimumab (another anti-CTLA-4 mAb) mediated intratumoral Treg depletion and CD8+-to-Treg ratio augmentation and promoted tumor rejection." (PMID 36816749, 2023). "blocks the interaction between CTLA4 and these ligands, CD80 and CD86, and keeps T cells remain active, which can recognize and kill tumor cells." (PMID 36949947, 2023). "Cancer cells have evolved to thwart T-cell activation by taking advantage of the inhibition role of this immune checkpoint since CTLA-4 and PD-LA1 antigens are commonly found on the surfaces of tumor cells." (PMID 37623035, 2023). "Evidence showed that the expression of CTLA-4 has a different prognostic effect in metastatic NSCLC lymph nodes versus primary tumors, which is mediated by phenotypical differences between the tumor microenvironments of lymph nodes and primary tumors." (PMID 37568193, 2023). "COL1A2 was positively correlated with CD274, CTLA-4, and PDCD1 based on TIMER data which was adjusted by tumor purity." (PMID 37805556, 2023). "Immune checkpoint proteins, including Programmed Death 1 (PD-1) and its ligands PD-L1 and PD-L2, Lymphocyte Activation Gene 3 (LAG-3), CD200, Cytotoxic T Lymphocyte Activator 4 (CTLA-4), and CD47, are involved in tumor immunology and benefit tumor growth." (PMID 37626420, 2023). "Our data supports a mechanism where CD80 is overexpressed by tumours cells after PDT, and sometimes also PD-L1 and CTLA-4." (PMID 37468749, 2023). "It is known that blocking immune checkpoint receptors such as PD-1/PD-L1 and CTLA-4 can alleviate CD8+T cell exhaustion and reactivate immune cell cytotoxicity to eliminate antigen-expressing tumor cells." (PMID 38299141, 2023). "First, B. longum 420 significantly augmented the anti-tumor activity in mice loaded with Renca, mouse RCC tumors treated with an anti-PD-1 antibody, and mice treated with anti-PD-1 and anti-CTLA-4 antibodies." (PMID 37340017, 2023). "First, CTLA4 regulates T-cell activation at the earliest stage in the lymph node, whereas PD1 limits T cells later in the tumor tissue." (PMID 37190054, 2023). "CD80 plays an important role in T-cell activation, exerting a dual effect on tumor immunity: it binds to CD28 to provide a costimulatory signal for T-cell activation, and it binds to CTLA-4, resulting in an immunosuppressive effect." (PMID 37765273, 2023). "We further analyzed the tumor microenvironment between different RiskScore groups, and it was also apparent that the expression of PDCD1, CD274, CTLA-4, HAVCR2 and LAG3 in the low-RiskScore group was relatively high." (PMID 37154982, 2023). "Here we show that tumor cell-derived exosomes (TEX) carrying surface PDL-1, PD-1, Fas, FasL, TRAIL, CTLA-4 and TGF-β1 induce apoptosis of CD8+T and CD4+T cells but spare B and NK cells." (PMID 37542121, 2023). "Conjugating PD-1 or CTLA-4 antibodies with ECM targeting agents, or fusing cytokines to ECM targeting agents for tumor localization have demonstrated positive pre-clinical results." (PMID 37662958, 2023). "The relationship between the expression levels of CD274, TIGIT, PDCD1, CTLA4 and LAG3 in tumor tissues of normal and LUAD patients and the relationship between each gene and the survival rate of LUAD patients." (PMID 36959799, 2023). "Within the same tumor, the T-cell repertoire (CD4, CD8) exhibits different subtypes of PD-1, CTLA-4, TIGIT, and more." (PMID 37376451, 2023). "The role of radiation in converting the tumor to anti-CTLA-4 responsiveness has been demonstrated, where the efficacy of anti-CTLA-4 antibody treatment was seen only after high dose intensity modulated radiation treatment [22, 23•]." (PMID 37979032, 2023). "Immune checkpoint molecules like CTLA4, PD1, PDL–1, LAG3, and TIM–3 inhibit the immune response in different tumor types at different phases of tumor development." (PMID 37056346, 2023). "PD-1, CTLA4, CD96, and TIGIT are important immune checkpoints that are potential targets for tumor immunotherapy." (PMID 36936375, 2023).